ERBB2 (erb-b2 receptor tyrosine kinase 2)
Diseases named in the same sentence as ERBB2 in open-access papers (continued):
Sharing a sentence is not in itself a finding about the gene and the disease.
tumor (continued). "HER2, an epidermal growth factor receptor protein encoded by the ERBB2 gene, has been found to be over-expressed as a tumour-associated antigen in 80% of GBM cells, signaling a poor prognosis, but not in normal neurons or glial cells." (PMID 37304305, 2023). "Here, we extended this approach to target UniCAR-NK-92 cells to cancer cells of solid tumor origin overexpressing the tumor-associated antigen ErbB2 (HER2)." (PMID 36688995, 2023). "Accordingly, we analyzed the correlation of the RNA transcript levels between ER-α encoding gene ESR1, PR encoding gene PGR, and HER2 encoding gene ERBB2 in tumor samples of BC patients." (PMID 36902278, 2023). "In contrast to full-length sema3E, p61-Sema3E induces the association of plexin-D1 with ErbB2 and the phosphorylation of ErbB2 and, as a result, induced tumor cell metastasis." (PMID 37627074, 2023). "Mutations of PTPN13 or ERBB2 in the primary tumor were correlated with significantly shorter PFS (P = 0.014 and 0.0034, respectively)." (PMID 37131253, 2023). "Since both PIK3CA and ErbB2 alterations reflect major driver events in tumor development, these results suggest that high RNA-protein correlations are associated with tumor functionality in the case of gene amplification." (PMID 37290530, 2023). "Increased synthesis of ErbB members including epidermal growth factor receptor EGFR, ErbB2, ErbB3, and ErbB4, which are associated with the development of solid tumours, such as tumours associated with breast, colorectal and ovarian cancer." (PMID 39935547, 2023). "In a previous study, ERBB2 protein (Her2/neu) expression has been significantly correlated with risk grade, tumour size, mitotic count, and increased risk of relapse in primary GIST." (PMID 37622176, 2023). "Human epidermal growth factor receptor (HER2) is a tyrosine kinase receptor encoded by the ERBB2 gene that is strongly implicated in tumor proliferation, differentiation, growth, and abrogation of apoptosis when amplified or overexpressed." (PMID 36826143, 2023). "ERBB2-mutant tumors have a higher tumor mutation burden (TMB) and microsatellite instability (MSI) than ERBB2 non-mutant tumors, but not all ERBB2-mutant tumors are TMB- and MSI-high." (PMID 37754252, 2023). "Our study demonstrates that tumor size, neural invasion, and vascular invasion were significantly associated with node metastases in ERBB2-positive GC patients." (PMID 36059809, 2022). "Our data indicate that mRNA expression of ATM/ERBB2 was significantly associated with tumour grade (p = 0.011), disease stage (p = 0.009) and tumour shape (p = 0.001)." (PMID 36056635, 2022). "We found that ERBB2 was highly expressed in PTC, and elevated ERBB2 expression was associated with iodine metabolism dysfunction, tumor proliferation, metastasis, angiogenesis, MEKi resistance, and poor prognosis." (PMID 36437939, 2022). "Noteworthy, within the Luminal A tumours a group of patients showed lower levels of ESR1 were associated with higher levels of ERBB2 signaling, especially when compared with other subtypes." (PMID 35985932, 2022). "In contrast, the fewer ERBB2 genes expressed in the tumor cluster, the more cancer-associated fibroblasts infiltrated into the immune cell cluster of LGG and CESC." (PMID 36172165, 2022). "Draw 1 analysis confirmed the ERBB2 mutation (L755S) identified in the tumor pathology report prior to treatment." (PMID 35181666, 2022).
tumor (continued). "The amplification of ERBB2 serves as a predictive and prognostic marker and is typically associated with tumor aggressiveness (high-grade tumor mitotic count), resistance to chemotherapy, distant metastases, and adverse clinical outcomes." (PMID 35742993, 2022). "The use of matched therapy was relatively low in patients with tumor alterations such as ERBB2 mutation (14/43, 32.6%), MET amplification (32/99, 32.3%), KRAS G12C (8/135, 5.9%), and EGFR exon 20 insertion (1/25, 4.0%)." (PMID 35877242, 2022). "The findings revealed that ERBB2 expression was significantly upregulated in most tumour types and was closely associated with tumour stage, grade, recurrence, prognosis, immune microenvironment and metabolic reprogramming." (PMID 35990657, 2022). "Although reports are conflicting, ERBB2 overexpression has been observed more commonly in tumors with an advanced T stage and high tumor mutational burden." (PMID 36291943, 2022). "For the HER 2 + tumor subtype, all genes implicated were located at chromosome 17q, where we distinguished relevant pathways such as the ERBB2, ERBB, and epidermal growth factor receptor (EGFR) or the negative regulation of ERBB." (PMID 36119512, 2022). "Activating mutations of ERBB2, which are mainly observed in the tyrosine kinase domain, lead to increased cell proliferation in vitro, rapid tumor growth in vivo, and sensitivity to HER2 targeted therapy, indicating their role as driver mutations." (PMID 34997908, 2022). "Owe to the research on ERBB2, multiple diagnostic and therapeutic methods were established for tumor management." (PMID 36437939, 2022). "Patient TOMAS-25 had three deleterious ARID1A indels, while patient TOMAS-26 tumor sample harbored a gain-of-function mutation in the ERBB2 gene, predicted as “possibly damaging” on protein function." (PMID 36110934, 2022). "This kataegis locus contained ERBB2 driver variants, which were detected in both tumour and ctDNA, and co-localised with ERBB2 amplification and copy number gains described previously." (PMID 35392854, 2022). "We then analyzed the co-mutations of 69 tumor driver genes with ERBB2 in 66 patients with ERBB2 fusions." (PMID 36276102, 2022). "Our patient exhibited ERBB2 amplification in addition to an ERBB2 E401G variant, suggesting that both ERBB2 mutation and amplification has led to tumor development." (PMID 34997908, 2022). "Conversely, failure of pET to achieve optimal suppression of tumor cell proliferation (post-pET Ki67 < 10%) was 1.8-fold more common in ERBB2-mutated ILC compared to ILC harboring wild-type ERBB2 (10/14, 71% versus 65/165, 39%, P = 0.0248)." (PMID 35842479, 2022). "In residual tumours following neoadjuvant anti-HER2-based chemotherapy, ERBB2 mRNA was associated with T-DM1 survival benefit in the KATERINE phase III trial." (PMID 34990895, 2022). "Subsequently, the association between ERBB2 expression and the abundance of tumour-infiltrating immune cells, such as CD4+ T cells, CD8+ T cells, B cells, neutrophils, dendritic cells (DCs) and macrophages, was analysed." (PMID 35990657, 2022). "This appears to explain the overrepresentation of ERBB2-mutated ILC among patients with tumor recurrences after adjuvant endocrine therapy." (PMID 35842479, 2022). "In general, most tumours have their own mutation profiles, and few genes are commonly found in all tumours although, like most other carcinomas, ERBB2/PI3K/AKT/mTOR are most affected." (PMID 35725812, 2022). "This change in the tumor architecture was associated with durable tumor rejection in murine Colon26 and ERBB2(+) mammary carcinoma models." (PMID 35155237, 2022). "In summary, we comprehensively analyzed ERBB2 gene mutations using the TCGA database concerning gene-phenotype, gene transcription, protein translation, and tumor-infiltrating immune cells." (PMID 36172165, 2022).
tumor (continued). "In IDC, the expression of PD-L1 and PD-1 in both stromal and tumour compartments was shown to be associated with the HER2-positive subtype and ERBB2 amplification." (PMID 35625798, 2022). "High SETD7-expressing tumours further exhibited a higher rate of ERBB2 mutation (20% vs. 5%) along with a poorer response to anti-Her2 therapy." (PMID 36551516, 2022). "Other emerging biomarkers which are under investigation are PIK3CA mutations, high level MET amplification, ERBB2 mutation, and Tumor Mutational Burden (TMB)." (PMID 34440689, 2021). "We tested the association of mutated genes with clinicopathological variables and found a significant association between ERBB2 mutation and tumor late stage (Fisher’s exact t-test; p value = 0.04)." (PMID 34207827, 2021). "Insights from ERBB3's role during mammary development can have implications for our understanding of tumor biology in the context of ERBB2/ERBB3 oncogenic mutation and/or amplification." (PMID 36618440, 2021). "Herein, the cytological study results showed that anti-HER antibody drugs, trastuzumab and pertuzumab, as well as small molecule kinase inhibitors, lenatinib, and lapatinib, elicited inhibitory effects on tumor cells harboring ERBB2 p.R678Q mutations." (PMID 33893247, 2021). "The inhibition of tumor growth by Bortezomib was associated with tumor necrosis and apoptosis, with the simultaneous inhibition of ErbB2, AKT, and with the induction of a strong intratumoral immune response." (PMID 34561494, 2021). "In this study, we investigated the clinicopathological characteristics and the frequency of co-occurrence of the CDH1 mutation and tumour-infiltrating lymphocytes (TILs) in 35 ERBB2-mutated BCs via a public database (TCGA-BRCA)." (PMID 34257600, 2021). "On the other hand, loss of ERBB2 amplification was observed in circulating tumor DNA in patients with primary resistance to T-DM1." (PMID 35008318, 2021). "Another case report study referred about the efficacy of ACT using CD4 T cells directed against the mutated ERBB2 protein expressed by the tumor cells in a patient with a metastatic epithelial cancer, mediating a successful tumor regression." (PMID 34064410, 2021). "Gene amplifications of CCND1, CDK12, CCNE1, and ERBB2 were identified in patients with low tumor mutational burden." (PMID 34068652, 2021). "The positive status of ERBB2 showed an association with advanced tumor-node-metastasis (TNM) stage (P = 0.035), positive lymphovascular invasion (P = 0.033), and high liver metastasis ratio (P = 0.025)." (PMID 34168152, 2021). "Pretreatment tumor molecular profiling identified multiple alterations including ERBB2 amplification and PIK3CA H1047R mutation." (PMID 34407844, 2021). "The main goal of our work was to create a vehicle for IFN-β delivery to the site of ErbB2-associated tumor cells." (PMID 34944558, 2021). "A novel ERBB3 TMD mutation I649R was found in tumor tissue of three patients with ERBB2 V659D (P03, P13, and P17)." (PMID 32478891, 2020). "Upregulation of ERBB2 (HER2) is associated with aggressive tumours, and poorer overall and disease-free survivals in breast cancer." (PMID 31959771, 2020). "The results demonstrated that acquired ERBB2/ERBB3 mutations by tumor cells are essential to induce checkpoint PD-L1, rendering tumor cells evasive from cytotoxic T cell immunity against tumor." (PMID 33028805, 2020). "ERBB2 amplification and mutations have been recognised as drivers in tumour development and progression." (PMID 32641355, 2020). "Receptor tyrosine-protein kinases ErbB2 (proto-oncogen) and ErbB3 (a dimer partner of ErbB2) were implicated in tumor growth, proliferation, and chemotherapeutic resistance." (PMID 33383894, 2020).
tumor (continued). "For the tumor-associated genes ERBB2 and CDK4, amplifications were, respectively, found in 6 (15.4%) tumor samples of our cohort." (PMID 32083130, 2020). "MEDICA treatment resulted in decrease in tumor number, weight, and volume; loss of ErbB1, ErbB2, and ErbB3 in breast tumors; and decrease in lung metastatic neu cells." (PMID 32695336, 2020). "One patient presented significant tumor enrichment of a germline variant in the oncogene ERBB2, in vitro expression of which caused downstream signaling pathway activation." (PMID 32295625, 2020). "D16ERBB2, a splice variant of ERBB2 generated through the skipping of exon 16, has been shown to exert high tumorigenecity, and a close association with increased tumor invasive properties and metastasis." (PMID 32793288, 2020). "The activating EGFR mutation L858R was identified in tumor tissue of two patients with either ERBB2 G660C (P22) or G660D (P26)." (PMID 32478891, 2020). "Our ERBB2 mutated tumor revealed a activating exon 21 mutation (c.2584 A > G p.T862A) which is sensitive to inhibition by neratinib and lapatinib." (PMID 30717682, 2019). "We use murine gallbladder derived organoids to demonstrate how activation of mutant Kras or ERBB2 in conjunction with loss-of-function of single or multiple tumor suppressor genes reliably leads to GBC in recipient mice." (PMID 31795490, 2019). "The RISK and RS also contain two genes overexpressed in Her2↑ tumours: ERBB2 (the gene coding for Her2) and GRB7 (the gene is linked to ERBB2 on chromosome 17)." (PMID 31174485, 2019). "Among these events, we concentrated on ERBB2 amplification, which has been associated with tumor sensitivity to HER2-targeted therapy." (PMID 31410192, 2019). "Proteins that contribute most strongly to the proteotype-based classification include INPP4B, CDK1, and ERBB2 and are associated with estrogen receptor (ER) status, tumor grade status, and HER2 status." (PMID 31315058, 2019). "In the ERBB2 cell model chosen for this analysis, p140Cap is causal in impairing in vivo tumor growth and metastasis formation." (PMID 31681758, 2019). "Overall, these data show that c-Src loss causes a tumor cell-intrinsic proliferation defect that significantly impairs ErbB2-driven mammary tumorigenesis." (PMID 31263101, 2019). "p140Cap is causal in dampening ERBB2-positive tumor cell progression, impairing tumor onset and growth, and counteracting epithelial mesenchymal transition, resulting in decreased metastasis formation." (PMID 31681758, 2019). "Tumor development occurs due to spontaneous mutations that activate the wild-type Neu gene (erbB2, HER2) to an oncogene." (PMID 31355130, 2019). "The CTC count was associated with ERBB2 status (p = 0.029) of the primary tumor as well as with the prevalence of bone metastases (p = 0.021)." (PMID 31481116, 2019). "Amplification of ERBB2 is known to be associated with an aggressive tumour phenotype, shorter disease-free survival and poor overall survival." (PMID 30898150, 2019). "Human epidermal growth factor 2 (HER2) is a proto-oncogene encoded by ERBB2 and associated with tumor cell proliferation and apoptosis." (PMID 30791934, 2019). "Studying the mtDNA content of the tumor samples according to the ERBB2 amplification status, a significant association was found in the ERBB2 amplified samples and a decreased level of the mtDNA content (P= 0.01)." (PMID 29743853, 2018). "In the phase 2 SUMMIT basket trial, 124 patients with v-erbB2 avian eryhtorblastic leukemia viral oncogene homolog 2 (HER2) mutations and 17 patients with HER3 mutations across 21 unique tumor types were treated with neratinib, a HER2/3 inhibitor." (PMID 29764494, 2018).
tumor (continued). "Concerning these 19 patients with a tumor type other than breast or oesogastric adenocarcinoma, 8 patients had an ERBB2 mutation and 11 had ERBB2 amplification." (PMID 29515767, 2018). "In recent years, there are some inconsistent views concerning the influence of ErbB2 dysregulation on the susceptibility of tumor cells to EGFR-TKIs in NSCLC." (PMID 29455669, 2018). "The 2 responders treated by chemotherapy plus trastuzumab had an ERBB2 S310Y mutated tumor, affecting the extracellular domain of HER2, confirming the preclinical demonstration of sensitivity to trastuzumab." (PMID 29515767, 2018). "Some studies indeed suggest an association of ERBB2 amplification with tumour size, lymph node metastasis, local invasion, and cancer stage; other studies instead do not find any link between them." (PMID 29094049, 2017). "ERBB2 amplification, mutation, and both alterations were detected in 22, two, and one tumor, respectively." (PMID 29089060, 2017). "In the double Tg mice, expressing both NeuT and p140Cap, p140Cap expression reduces tumour burden, indicating that p140Cap is causative in limiting ERBB2 tumorigenic features in vivo." (PMID 28300085, 2017). "Cellular- and receptor-specific glycan profiling of ErbB2-overexpressing NCI-N87 cells unveiled a heterogeneous glycosylation pattern harboring the tumor-associated sialyl Lewis a (SLea) antigen." (PMID 29143776, 2017). "This study identified ErbB2 as a previously unreported protein carrier of the tumor-associated SLea epitope." (PMID 29143776, 2017). "While ERRα deficiency significantly delays tumor formation in a mouse model of ErbB2-induced mammary tumorigenesis." (PMID 26871469, 2016). "Of interest, MET/CEN7 gain or loss had little association with ERBB2 gene status but was associated with patient age and trended with tumor size and PR expression." (PMID 27576528, 2016). "In tumor cells, NN drives a stable, homotypic association of ErbB3, which traps ErbB3, keeping it away from undesirable oncogenic signaling with ErbB2." (PMID 27596216, 2016). "We did not observe changes in ERBB2 amplification status in the majority (7/9 or 78%) of our tumours, consistent with previous reports of loss of HER2-positivity occurring in only 12%–32% of patients undergoing anti-HER2 therapy." (PMID 27923043, 2016). "In the present study, we describe yet another important adaptation mechanism operating in ErbB2-dependent tumour cells, which causes the reactivation of the PI3K/AKT pathway even in the presence of de-phosphorylated ErbB3 receptor." (PMID 27255951, 2016). "High expression was associated with poor-prognosis features (large tumor size, high grade, ER-negative, PR-negative, ERBB2-positive status, high proliferation, basal and ERBB2-enriched subtypes)." (PMID 25669979, 2015). "In contrast, 80% of HGG (124 of 155 samples) tumors are strongly associated with luminal-B, ERBB2+, and basal molecular tumor subtypes (Chi-square p-value = 2.8 × 10−45)." (PMID 26474389, 2015). "ERBB2 is a member of the epidermal growth factor receptor (EGFR) family that is associated with increased proliferation of tumor cells." (PMID 24926380, 2014). "These tumours were characterised by increased phosphorylation of several signalling molecules known to associate with erbB2, including Ptpn11, Plcγ1, Cbl and CrkL, as well as its heterodimerisation partner Egfr." (PMID 25200860, 2014). "An additional complicating factor is the association between ErbB2-IR and the Ki67 index, given that the rate of cell proliferation is significantly higher for cases with tumour stage 3–4 than tumour stage 2 in the tissue microarray." (PMID 25215939, 2014). "The significant association of tumour ErbB2-IR with the Gleason score at diagnosis was lost when controlled for the association of both parameters with Ki-67." (PMID 25215939, 2014).